RAI2 (retinoic acid induced 2)
Tractability: Small molecule: a structure with a bound ligand is known. Antibody: the Human Protein Atlas places it where antibodies can reach. PROTAC: ubiquitination databases record sites on it.
Gene: Protein-coding gene on chromosome X (17,799,788 to 17,861,337, reverse strand). Ensembl gene ENSG00000131831.
Subcellular location (Human Protein Atlas): Plasma membrane
Gene Ontology:
Molecular function: protein binding
Biological process: animal organ development; embryo development ending in birth or egg hatching
Cellular component: nucleus
Gene-disease validity (ClinGen):
ClinGen rates the evidence that RAI2 causes each of these diseases.
congenital heart disease (autosomal dominant): Disputed. A heart disease that is present at birth.
Homologues: Orthologues: macaque RAI2 (98% identical), rat Rai2 (90% identical), guinea pig RAI2 (90% identical), mouse Rai2 (89% identical), dog RAI2 (87% identical), pig RAI2 (86% identical), rabbit RAI2 (81% identical), tropical clawed frog rai2 (59% identical), Drosophila melanogaster Sobp (13% identical). Paralogues in human: SOBP (22% identical).
Diseases named in the same sentence as RAI2 in open-access papers:
RAI2 is named in the same sentence as 30 diseases in open-access papers, as found by Europe PMC text mining. Sharing a sentence is not in itself a finding about the gene and the disease. The quoted sentences say what the papers report.
breast carcinoma (11 papers, 2018 to 2025). "RAI2 depletion in breast cancer cell lines resulted in loss of mitotic fidelity characterized by prolonged mitosis with increased chromosome segregation errors and micronuclei formation." (PMID 40696381, 2025). "It is worth noting that previous studies have shown that decreased RAI2 expression is linked to poor prognosis in colorectal cancer and breast cancer." (PMID 38117798, 2023). "Werner and colleagues showed that the depletion of RAI2 in luminal breast cancer ER+ cells is associated with a loss of epithelial differentiation that increases invasiveness." (PMID 32012980, 2020). "To assess whether RAI2 expression is associated with genomic instability in breast cancer patients, we performed an analysis of large published clinical datasets." (PMID 40696381, 2025). "RAI2 was initially identified as a novel metastasis suppressor protein specifically associated with the presence of disseminated tumour cells in the bone marrow of breast cancer patients, but its molecular function is largely unknown." (PMID 40696381, 2025). "In conclusion, we have shown that RAI2 depletion sensitizes KPL-1 and MCF-7 breast cancer cells to treatment with topoisomerase I and Aurora A inhibitors, indicating an additive effect with RAI2 inactivation." (PMID 40696381, 2025). "For validation a correlation of RAI2 gene expression with the complete CIN70 score was assessed in the METABRIC breast cancer dataset." (PMID 40696381, 2025). "Drug screening revealed increased sensitivity of RAI2-depleted breast cancer cells to topoisomerase I and Aurora A inhibitors." (PMID 40696381, 2025). "We discovered three distinct related phenotypes in RAI2-depleted breast cancer cells that are indicative of such premature entry into mitosis: (i) de novo micronuclei formation, (ii) prolonged mitosis, and (iii) mis-segregation of acentric chromosomes." (PMID 40696381, 2025). "RAI2, a recently recognized tumour suppressor, is believed to have major parts in the progression and metastasis of quite a few of malignancies including breast cancer, colorectal cancer, bladder cancer, and prostate cancer." (PMID 37899172, 2023). "Some studies used invasive breast cancer tissues to indicate that lower RAI2 mRNA and protein were independent risk factors for lower shorter disease-free survival (DFS), and breast-cancer-specific survival (BCSS)." (PMID 37064084, 2023). "RAI2 has been proven to suppress early hematogenous dissemination of breast cancer and indicate favorable prognosis by analyzing hundreds of breast cancer patient samples." (PMID 37064084, 2023). "In a recent study, multivariate analyses indicated that both RAI2 mRNA and RAI2 protein expression were independent risk factors for both disease-free survival (DFS) and breast-cancer-specific survival (BCSS) in breast cancer patients." (PMID 35299743, 2022). "As an important development-related gene, RAI2 has also been proved to serve as a key tumor suppressor in breast cancer and CRC." (PMID 35299743, 2022). "We analysed the consequences of RAI2 depletion on gene expression and genomic stability in luminal breast cancer cell lines, performed cytotoxicity profiling using a library of pharmacologically active compounds, and characterized a potential function of the RAI2 protein in the DNA damage response." (PMID 40696381, 2025). "Subsequent studies have also demonstrated the prognostic value of RAI2 in breast cancer." (PMID 38041134, 2023). "Our results showed that the normal tissues had more RAI2 expression than breast cancer tissues." (PMID 37064084, 2023). "Furthermore, more samples are needed to validate the effects of RAI2 on prognosis for breast cancer patients and RAI2-related pathways should be clarified." (PMID 37064084, 2023).
breast carcinoma (continued). "Whether RAI2 can predict bone metastasis in breast cancer requires further validation in clinical samples." (PMID 38041134, 2023). "RAI2 has been identified as an emerging tumor suppressor in breast cancer and colorectal cancer." (PMID 37064084, 2023). "In this study, we performed systematic analyses of RAI2 in breast cancer." (PMID 37064084, 2023). "The present study may contribute to understanding the molecular mechanisms of RAI2 and enriching biomarkers to predict patient prognosis in breast cancer." (PMID 37064084, 2023). "The primary RAI2 amino acid sequence has two highly orthologically conserved sequences (ALDLS) in the internal region (amino acids 316–320 and 342–346 in human sequence) of the RAI2 protein, and It was reported that RAI2 can interact with CtBP2 by ALDLS domain in breast cancer." (PMID 35299743, 2022). "Different authors described RAI2 as tumor suppressor in breast cancer." (PMID 32012980, 2020). "It has been reported that depletion of RAI2 activated the AKT signaling cascade in breast cancer." (PMID 29796120, 2018). "The expression of RAI2 has been reported to be reduced in breast cancer." (PMID 29796120, 2018). "Reduced expression of retinoic acid-induced 2 (RAI2) was found in breast cancer." (PMID 29796120, 2018). "Moreover, RAI2 has been reported to play a role in the metastasis of breast cancer, and the expression of RAI2 may be a promising candidate biomarker for breast cancer patient prognosis." (PMID 36276278, 2022). "In addition, RAI2 depletion appears to have additive effects with anticancer agents that induce DNA damage, which may further influence the response to chemotherapeutic treatment or metastatic relapse in human breast cancer." (PMID 40696381, 2025). "It was reported that RAI2 can interact with CtBPs, especially CtBP2, through ALDLS domains and inhibit the transcriptional repression effect of CtBP2 on target genes in breast cancer." (PMID 35299743, 2022). "Retinoic acid-induced 2 (RAI2) is a novel tumor suppressor gene whose expression is downregulated in various types of cancer, including breast cancer and CRC." (PMID 33477997, 2021). "For example, RAI2, which does not belong to the PAM50 gene list, was selected in the analysis, and it could play a role in helping to classify molecular subtypes of breast cancer." (PMID 36077657, 2022).
colorectal cancer (7 papers, 2018 to 2023). A primary or metastatic malignant neoplasm that affects the colon or rectum. "The promoter region methylation is correlated with loss of/reduced expression of RAI2 in colorectal cancer cells." (PMID 29796120, 2018). "The expression of RAI2 in human colorectal cancer is regulated by methylation in its promoter region, and RAI2 methylation is an indicator of poor prognosis for patients with colorectal cancer." (PMID 37899172, 2023). "In this study, we identified that RAI2 is a novel antagonist of Wnt/β-catenin signaling pathway and a potential biomarker of chemosensitivity in colorectal cancer." (PMID 35299743, 2022). "A previous study showed that the expression of RAI2 was downregulated and that it was hypermethylated in colorectal cancer." (PMID 36276278, 2022). "Analysis of RAI2 expression status with OS or RFS in colorectal cancer patients by Cox regression analysis." (PMID 35299743, 2022). "We have reported the reduced expression of RAI2 regulated by promoter region methylation in colorectal cancer in our previous study." (PMID 35299743, 2022). "Further, our previous study demonstrated that RAI2 served as a tumor suppressor in colorectal cancer by inhibiting proliferation and promoting apoptosis of CRC cells, and the expression of RAI2 was down-regulated by promoter region methylation." (PMID 35299743, 2022). "In this study, we detected the expression of RAI2 in 298 cases of colorectal cancer patients by IHC." (PMID 35299743, 2022). "To clarify the effect of RAI2 on Wnt signaling, we detected the luciferase activity of Wnt/β-catenin signaling before and after RAI2 transfection in colorectal cancer cells LoVo and HCT116, respectively." (PMID 35299743, 2022). "Available data were obtained from 373 cases of colorectal cancer samples for both RAI2 expression and methylation." (PMID 29796120, 2018). "The effects of RAI2 on cell cycle and apoptosis were analyzed by flow cytometry in human colorectal cancer cells." (PMID 29796120, 2018). "By analyzing The Human Protein Atlas, we found that RAI2 was highly expressed in normal human colonic tissue samples, and its expression levels were reduced in colorectal cancer samples." (PMID 29796120, 2018). "Clinical characteristics and RAI2 expression status of 298 patients with colorectal cancer." (PMID 35299743, 2022). "In addition, low expression of RAI2 was reported as a poor prognostic marker in breast and colorectal cancer." (PMID 36077657, 2022). "Low expression of RAI2 was found in 33.89% (101/298) of the colorectal cancer samples, and the expression of RAI2 was positively correlated with phosphorylated β-catenin (r=0.8866, P<0.0001), which is further validation of the inhibitory effect of RAI2 on Wnt/β-catenin signaling." (PMID 35299743, 2022). "Moreover, RAI2 increased the chemosensitivity of colorectal cancer cells to oxaliplatin and fluorouracil." (PMID 35299743, 2022). "RAI2 was methylated in 53.6% (127/237) of primary colorectal cancer." (PMID 29796120, 2018). "RAI2 may serve as a potential biomarker of chemosensitivity in colorectal cancer." (PMID 35299743, 2022). "Our work provides evidence that silence or down-regulation of RAI2 in colorectal cancer may contribute to aberrant activation of Wnt signaling pathway, and consequently promote chemoresistance of CRC cells to chemotherapy drugs such as oxaliplatin and fluorouracil." (PMID 35299743, 2022). "The regulation and function of RAI2 in human colorectal cancer (CRC) remain unclear." (PMID 29796120, 2018). "Retinoic acid-induced 2 (RAI2) is a newly discovered tumor suppressor, and RAI2 promoter region methylation has been reported to indicate poor prognosis in colorectal cancer, RAI2 downregulated expression or hypermethylation has been identified in colorectal cancer." (PMID 36276278, 2022).
colorectal cancer (continued). "In addition, we found that RAI2 inhibits the stem cell-like properties of CRC cells and increases the chemosensitivity of colorectal cancer cells to oxaliplatin and fluorouracil, which revealed that RAI2 may serve as a potential biomarker of chemosensitivity in colorectal cancer." (PMID 35299743, 2022).
colon cancer (4 papers, 2018 to 2025). "Restoration of RAI2 expression has been linked to cell apoptosis induction and a good prognosis of colon cancer." (PMID 33477997, 2021). "By using six publicly available datasets, the authors found that lower RAI2 transcript expression was associated with shortened OS in breast, lung, ovarian, and colonic cancer." (PMID 29796120, 2018). "In colon cancer, restoration of RAI2 expression suppressed CRC cell proliferation, migration, and invasion, as well as induced programmed cell death." (PMID 33477997, 2021). "Re-expression of RAI2 in human colon cancer cells (HCT116 and LoVo) suppressed the fluorescent activity of Wnt signaling, increased the phosphorylation and inhibited nuclear translocation of β-catenin, with down-regulation of target genes like c-Myc, CyclinD1, ASCL2, and LGR5." (PMID 35299743, 2022).
lymph node metastasis (3 papers, 2018 to 2023). "According to univariate analysis, RAI2 methylation, tumor differentiation, lymph node metastasis, and TNM stage were associated with both poor 5-year OS (all P < 0.05) and 5-year RFS (all P < 0.05)." (PMID 29796120, 2018). "RAI2 was frequently methylated in human primary CRC, and methylation of RAI2 was significantly associated with female gender, TNM stage, and lymph node metastasis." (PMID 29796120, 2018). "Methylation of RAI2 was significantly associated with gender (P < 0.001), TNM stage (P < 0.001), and lymph node metastasis (P < 0.001)." (PMID 29796120, 2018). "Previous studies found that there was no relation between RAI2 level and lymph node metastasis." (PMID 37064084, 2023).
bladder cancer (2 papers, 2021 to 2023). "For example, circRBPMS inhibits bladder cancer progression by regulating RAI2 expression through sponging miR-330-3p." (PMID 34346842, 2021).
Nance-Horan syndrome (2 papers, 2018 to 2021). A syndrome characterized by the association in male patients of congenital cataracts with microcornea, dental anomalies and facial dysmorphism. "Retinoic acid-induced 2 (RAI2) is located in human chromosome Xp22.13, a region in which microdeletion has been identified in Nance-Horan syndrome (NHS)." (PMID 29796120, 2018).
prostate carcinoma (2 papers, 2023 to 2024). A carcinoma that arises from epithelial cells of the prostate gland. "The impact of RAI2-mediated CtBP loss-of-function is illustrated by the analysis of a diverse cohort of prostate cancer patients, which reveals a substantial decrease in RAI2 in advanced treatment-resistant cancer subtypes." (PMID 38898011, 2024).
breast tumors (1 paper, 2025). "Analysis of clinical samples revealed that in primary breast tumours, low RAI2 gene expression is significantly associated with genomically unstable tumours and poor prognosis." (PMID 40696381, 2025). "Thus, we could confirm that primary breast tumors with putative DNA DSB repair deficiency have low RAI2 gene expression." (PMID 40696381, 2025). "Taken together these results confirm that compared to other genes in the genome there is a strong correlation between low RAI2 gene expression and different characteristics of genome instability in primary breast tumors." (PMID 40696381, 2025).
embryonal carcinoma (1 paper, 2023). A non-seminomatous malignant germ cell tumor characterized by the presence of large germ cells with abundant cytoplasm resembling epithelial cells, geographic necrosis, high mitotic activity, and pseudoglandular and pseudopapillary structures formation. "Retinoic acid-induced 2 (RAI2) is induced by RA in embryonal carcinoma cells and involved in cellular differentiation." (PMID 37064084, 2023).
tumor (11 papers, 2015 to 2025). "In this research, the TIMER website was used to examine the causal connection between tumour infiltration levels and specific somatic copy number alterations for RAI2." (PMID 37899172, 2023). "By multivariate analysis, RAI2 methylation, tumor differentiation, and TNM stage were associated with both poor 5-year OS and 5-year RFS (all P < 0.05)." (PMID 29796120, 2018). "Moreover, the association between RAI2 expression and the abundance of six tumor-infiltrating immune cells was investigated by TIMER, including B cells, CD8+ T cells, CD4+ T cells, B cells, dendritic cells, neutrophils, and macrophages." (PMID 37064084, 2023). "Moreover, the immune infiltration analysis indicated that low expression of RAI2 in GC was associated with a higher intensity of tumor-infiltrating lymphocytes (TILs) and an abundance of Programmed death ligand 1 (PD-L1) expression." (PMID 37899172, 2023). "To study the effects of RAI2-induced CtBP polymerization in a relevant tumor cell model, we chose the VCaP PC cell line because of its high endogenous RAI2 expression and hence the presence of distinct CtBP/RAI2 foci." (PMID 38898011, 2024). "Retinoic acid-induced 2 (RAI2) is an innovative tumor suppressor and as a newly discovered gene, little has been discovered regarding the way it works biologically." (PMID 37899172, 2023). "To identify the level of RAI2 expression in distinct types of tumours, we initially analyzed the TCGA database." (PMID 37899172, 2023). "The analyses results indicated that RAI2 expression was negatively related to tumor purity of BRCA (r = -0.136, p < 0.001), BRCA-basal (r = -0.401, p < 0.001), BRCA-HER2 (r = -0.136, p < 0.001) and BRCA-luminal (r = -0.261, p < 0.001) subtypes." (PMID 37064084, 2023). "We observed that DFS periods were significantly shorter (log-rank test; p = 6.75 x 10−19) for patients with tumours expressing low RAI2 levels than those with high RAI2 expression." (PMID 38117798, 2023). "We utilized the gene module of TIMER datasets to determine the relation of RAI2 expression with tumor-infiltrating lymphocytes for BRCA patients." (PMID 37064084, 2023). "Here, we report a novel tumor suppressor, retinoic acid-induced 2 (RAI2), which is located in the Xp22 region of the chromosome and plays a role in inhibiting GC growth and invasion." (PMID 37899172, 2023). "Tumor sphere formation assay showed that CD133+ cells with RAI2 re-expressed formed fewer and smaller spheres than the control group (P=0.0285 in LoVo, P=0.0048 in HCT116), suggesting that RAI2 inhibited the self-renewal ability of CRC cells." (PMID 35299743, 2022). "Various degradative enzymes, either in the tumor cells or in host cells, are induced to do so by tumor-derived factors related to retinoid signaling such as RAI2 or through retinoid-independent metastasis modulators such as WRN, IGF1-R, TGF-β1 and E-cadherin." (PMID 33477997, 2021). "The tumor weight was reduced significantly after the restoration of RAI2 expression in RKO cells (P < 0.001)." (PMID 29796120, 2018). "The tumor volume was significantly reduced after the restoration of RAI2 expression in RKO cells (P < 0.01)." (PMID 29796120, 2018). "Additionally, patients with tumours expressing low RAI2 levels had the shortest significant OS duration (OS = 68.48 months) compared to those with high expression of this gene (OS = 174.84 months)." (PMID 38117798, 2023). "We found that RAI2 could decrease the proliferation and invasion in GC cells through reducing PD-L1 expression and related to tumor-infiltrating lymphocytes (TILs), suggesting that it may be an innovative treatment option for GC patients." (PMID 37899172, 2023). "Furthermore, we validated the low expression of RAI2 in tumor samples by analyzing 27 paired samples from TCGA STAD datasets (P < 0.01)." (PMID 37899172, 2023). "Retinoic acid-induced 2 (RAI2) was proved to be a tumor suppressor in CRC in our previous report." (PMID 35299743, 2022).